MDM2 (MDM2 proto-oncogene)
Diseases named in the same sentence as MDM2 in open-access papers (continued):
Sharing a sentence is not in itself a finding about the gene and the disease.
prostate carcinoma (continued). "In addition to an increased level of pAMPK, which has been previously reported in a prostate carcinoma cell line transfected with RPS19-specific small interfering RNAs31, we observed an increase in MDM2 expression." (PMID 28931864, 2017). "Here we describe a mechanism by which the AR can be targeted for destruction in prostate cancer cells, in a manner that does not directly inhibit the AR itself or androgen metabolism, using MDM2 antagonists." (PMID 27729622, 2016). "In a case–control study we determined the distribution of the Mdm2 SNP309 in 145 male subjects with prostate cancer and in 124 male controls without any malignancy using RFLP analysis." (PMID 18577987, 2008). "Accordingly, a clinical trial was conducted in the United Kingdom with idasanutlin (RO5503781), another inhibitor of MDM2, alongside abiraterone and prednisolone or enzalutamide, and that combination was expected to help men with prostate cancer who were no longer responding to hormone therapy." (PMID 30700046, 2019). "However, BMI1 exerts also some important oncogenic effects in prostate cancer cells through PRC1-independent mechanisms, involving direct binding to AR and consequent inhibition of MDM2-mediated AR degradation and sustained AR signaling in prostate cancer cells." (PMID 31366128, 2019). "To assess whether the disruption of the NFAT1-MDM2 P2 promoter complex by InuA could inhibit MDM2 transcription, we examined the MDM2 mRNA expression and the protein expression of NFAT1 and MDM2 in prostate cancer cells transfected with NFAT1 siRNA or control siRNA." (PMID 29311926, 2017). "However, the results from the MDMX KD prostate cancer cells not only validated the importance of MDMX for InuA-induced MDM2 degradation, but also implied the existence of other molecular mechanisms, such as inhibition of MDM2 transcription, that contribute to InuA’s inhibitory effects on MDM2." (PMID 29311926, 2017). "In the present study, we prepared and characterized a novel nano-delivery system for the oral administration of a natural MDM2 inhibitor, GS25, and evaluated its pharmacokinetics, toxicity, and efficacy in preclinical models of human prostate cancer." (PMID 26041888, 2015).
leukemia (99 papers, 2004 to 2026). A malignant (clonal) hematologic disorder, involving hematopoietic stem cells and characterized by the presence of primitive or atypical myeloid or lymphoid cells in the bone marrow and the blood. "MDM2 rs2279744 genetic variant was implicated in a high risk of salivary gland cancers, TCs, and leukemias." (PMID 36009531, 2022). "Eliminating MDM4 and MDM2 by MMRi62 hits the key drug targets in AML because MDM4 is a pervasive driver of leukemogenesis in multiple mouse leukemia models, and MDM2 overexpression induced by MTF2 loss is a mediator for refractory AML." (PMID 35992795, 2022). "MD-265 is a potent and specific MDM2 degrader with broad pre-clinical activity and a promising drug candidate for the treatment of leukemias." (PMID 41986621, 2026). "After extensive optimization, the most potent WB214 was shown to have an impressive MDM2‐degradation activity with DC50 value of 4.1 nM against leukemia cells." (PMID 37261210, 2023). "The most active compound MD‐224 (CRBN‐3) effectively induced rapid degradation of MDM2 at the concentrations <1 nM in human leukemia cell lines." (PMID 37261210, 2023). "Depleting KDM4A and KDM4C by either shRNA or SD49-7 enhanced trimethylation of H3K9 occupying the promoter of MDM2 and activated p21CIP1 by decreasing MDM2 expression, inhibiting the stemness and proliferation, and activating apoptosis of leukemia cells." (PMID 35836814, 2022).
leukemia (continued). "generated MDM2-specific high-affinity TCR redirecting CTL in the context of HLA-A*02:01 for targeting leukemia." (PMID 35356211, 2022). "As a powerful compound with a future in the treatment of leukemia, this peptide MDM2-based PROTAC is proof of the enormous potential that the association of target degradation with the recruitment of MDM2 can offer, not just in those of a chemical origin." (PMID 36232374, 2022). "A PROTAC for MDM2, for example, consists of a nutlin-based MDM2 ligand joined to the E3 ubiquitin ligase cereblon (CRBN; CRL4CRBN) via a short linker and promotes efficient degradation of MDM2 in leukemia cells." (PMID 33825941, 2021). "In general, monotherapy with MDM2 inhibitors revealed very modest anti-leukemia effect in R/R AML, including RG7112, RO6839921 (an inactive pegylated prodrug of idasanutlin), and AMG-232." (PMID 33757574, 2021). "Considering the fact that there is an overexpression of MDM-2 in a large number of leukemias, lowering the level of MDM-2 will mean favoring cell death." (PMID 32486249, 2020). "Recently, MDM2 inhibitor Nutlin-3 has attracted some attention in the field of leukemia as an anti-tumor agent." (PMID 25880782, 2015). "In our opinion, this cell type-specific effect of MMRi64 on Mdm2 and MdmX makes it a very unique compound for leukemia/lymphoma treatment." (PMID 26720344, 2015). "Nevertheless, iron-dependent downregulation was revealed in leukemia cell lines and primary human cells derived from acute myeloid leukemia patients, suggesting a cell-type-specific regulation of Mdm2 by iron." (PMID 37561022, 2023).
leukemia (continued). "In addition, the PROTAC-based MDM2 degrader MD-224 effectively induces rapid degradation of MDM2 and achieves tumor regression in an in vivo leukemia xenograft tumor model." (PMID 38201233, 2023). "Consequently, MD-224 is a promising and highly efficient MDM2 degrader with potential for treating human leukemia and other cancers." (PMID 37669923, 2023). "As expected, MMRi62 increased ubiquitinated species of MDM2B and MDM4 (smearing ladders of protein bands above MDM2B or MDM4 bands), which is consistent with the result that only MMRi62 induced proteasomal degradation of MDM4 and MDM2 proteins in leukemia cells." (PMID 35992795, 2022). "MD-224 effectively induced MDM2 degradation at subnanomolar concentrations in human leukemia cells." (PMID 31885879, 2019). "In addition, overexpression of MDM2 is detected in many malignancies, such as leukemia, that lack MDM2 gene amplification: The mechanism by which MDM2 is overexpressed in cancers in the absence of gene amplification is not completely known." (PMID 25888903, 2015). "In leukemia cells, MMRi64 potently induces downregulation of Mdm2 and MdmX." (PMID 26720344, 2015). "Therefore, MDM2 appears to be a promising therapeutic target with which to sensitize TKI-resistant BCR-ABL1 positive leukemia cells to TKI-induced apoptosis." (PMID 24349524, 2013). "However, whether MMRi62 selectively kills MDM2-high or MDM4-high leukemia cells needs to be verified in the future." (PMID 35992795, 2022).